PIWIL1 (piwi like RNA-mediated gene silencing 1)
Diseases named in the same sentence as PIWIL1 in open-access papers (continued):
Sharing a sentence is not in itself a finding about the gene and the disease.
multiple myeloma (4 papers, 2021 to 2026). "However, the exact function of PIWIL1 in multiple myeloma (MM) and the underlying mechanism remain unclear." (PMID 35083142, 2021). "In myeloma cells, PIWIL1 overexpression resulted in higher cell viability and resistance to bortezomib, dexamethasone, and doxorubicin in vitro due to the activation of autophagy and mitophagy." (PMID 38303021, 2024). "Further research should be undertaken to investigate more downstream molecular target regulated by PIWIL1 relating to mitophagy and myeloma stem cells." (PMID 35083142, 2021). "In summary, here we identified a novel functional mechanism by which PIWIL1 confers chemotherapeutic drug resistance by activating mitophagy and the myeloma stem cell population through AKT-mTOR and PARKIN-dependent mitophagy pathways." (PMID 35083142, 2021). "Here, we revealed that PIWIL1 was highly expressed in myeloma cell lines and newly diagnosed MM patients, and that its expression was notably higher in refractory/relapsed MM patients." (PMID 35083142, 2021). "The PIWI-like RNA-mediated gene silencing 1 (PIWIL1) protein activates mitophagy and induces doxorubicin resistance in multiple myeloma cells." (PMID 36289190, 2022). "In the present study, PIWIL1 was found to modulate autophagy-related proteins LC3, p62, and mTOR and the canonical PINK1/PARKIN pathway proteins, indicating that PIWIL1 promoted myeloma growth by modulating autophagy/mitophagy." (PMID 35083142, 2021). "The upregulation of PIWIL1 led to an increase, while its downregulation resulted in a decrease in the side population and expression of the stemness genes such as NANOG, SOX2, and POU5F1 in human myeloma cells." (PMID 38303021, 2024).
colonic adenoma (3 papers, 2021 to 2022). "Both PIWIL1 and piRNAs are overexpressed in CRC, and an upward trend was observed in PIWIL1 expression levels during the colon adenoma–carcinoma sequence." (PMID 34070617, 2021).
preeclampsia (3 papers, 2022 to 2024). Preeclampsia is a hypertensive disorder of pregnancy that is characterized by new-onset hypertension with proteinuria presenting after 20 weeks of gestation, and depending on mild or severe forms may initially present with severe headache, visual disturbances, and hyperreflexia. "We further investigated the role of PIWIL1 by overexpressing and silencing its expression in vitro to obtain evidence for the association of PIWIL1/piRNA with the development and progression of preeclampsia." (PMID 35464758, 2022). "Again, data were not concordant, with one study demonstrating differential expression of PIWIL1 protein in preeclampsia placentas, where the other reported PIWIL1 mRNA to be around the lower limit of detection in placental tissue using qPCR." (PMID 38955620, 2024). "The first study went on to confirm PIWIL1 expression was lower in preeclampsia villous trophoblast cells through immunohistochemistry and Western blotting." (PMID 38955620, 2024). "Quantitative analysis revealed that PIWIL1 expression was significantly lower in placental tissues from pregnancies with preeclampsia than in tissues from normal pregnancies." (PMID 35464758, 2022). "Subsequently, we detected the expression of PIWIL1 in 35 preeclampsia and 29 normal placental tissues." (PMID 35464758, 2022). "Western blotting confirmed the decreased expression of PIWIL1 in the placental tissue of pregnancies with preeclampsia." (PMID 35464758, 2022). "PIWIL1 expression was reduced in patients with preeclampsia, and silencing of PIWIL1 expression inhibited the proliferation and invasion of trophoblasts and promoted the apoptosis of placental trophoblast cells." (PMID 35464758, 2022). "We observed that PIWIL1 was mainly expressed in placental villous trophoblast cells, and its expression was reduced in pregnancies with preeclampsia." (PMID 35464758, 2022). "PIWIL1 is reduced in preeclampsia, inhibits the proliferation of trophoblast cells, and promotes apoptosis of placental trophoblast cells, leading to shallow placenta accreta and the development of preeclampsia." (PMID 38031146, 2023). "This study is aimed at investigating the role of PIWIL1/piRNA in the development of preeclampsia." (PMID 35464758, 2022). "PIWIL1/piRNA may be involved in the pathogenesis of preeclampsia by inhibiting the proliferation and invasion and promoting the apoptosis of placental trophoblasts." (PMID 35464758, 2022). "Additionally, immunohistochemical staining indicated that PIWIL1 expression was markedly decreased in the placental villous trophoblasts of patients with preeclampsia." (PMID 35464758, 2022). "We hypothesized that piRNA regulation would affect the expression of target genes, thereby indirectly regulating the expression of the PIWIL1 gene in placental trophoblast cells, resulting in shallow placental implantation and the occurrence of preeclampsia." (PMID 35464758, 2022). "Therefore, we speculated that PIWIL1 might be involved in the pathogenesis of preeclampsia by repressing the proliferation and invasion of trophoblasts, resulting in shallow implantation of the placenta and poor remodeling of the spiral arteries." (PMID 35464758, 2022). "Therefore, PIWIL1/piRNA pathway may be a potential target in preeclampsia in the future." (PMID 35464758, 2022). "Therefore, we speculated that PIWIL1/piRNA plays a vital role in the development of preeclampsia." (PMID 35464758, 2022). "However, the role of PIWIL1/piRNA in preeclampsia has not been investigated." (PMID 35464758, 2022).
Alzheimer disease (2 papers, 2022 to 2023). A progressive, neurodegenerative disease characterized by loss of function and death of nerve cells in several areas of the brain leading to loss of cognitive function such as memory and language. "In Seo's study, the SNP rs10848087 located in the 5'-UTR of PIWIL1 was identified as a high-quality SNV associated with Alzheimer's disease susceptibility genes and significant associations with hippocampal volume (Hv) in vivo AD pathologies." (PMID 38012622, 2023). "Likewise, a recent study using postmortem samples of brains of Alzheimer’s disease patients showed upregulation of PIWIL1." (PMID 35015250, 2022).
cancer testis (2 papers, 2019 to 2023). "In particular, PIWIL1 has been recently listed among the extremely high-expressed cancer testis genes (EECTGs) and are considered as a potential epi-drivers in tumors." (PMID 31694219, 2019).
chronic myeloid leukemia (2 papers, 2019 to 2023). "In contrast, the overexpression of PIWIL1 seems to have a beneficial effect in chronic myeloid leukemia, since it is able to inhibit the growth and migration of tumor cells and increases sensitivity to daunomycin." (PMID 31443431, 2019). "As to leukemia, the function of PIWIL1 is only reported in chronic myeloid leukemia." (PMID 38023199, 2023). "In contrast, PIWIL1 expression downregulates MMP-2 and MMP-9 and inhibits the proliferation and migration ability of chronic myeloid leukemia cells." (PMID 31443431, 2019).
ductal adenocarcinoma of the pancreas (2 papers, 2015 to 2024). "One study on pancreatic ductal adenocarcinoma (PDAC) cell lines demonstrated that PIWIL1 acts as an oncoprotein by activating the APC/C E3 complex, enhancing PDAC metastasis through the targeted degradation of the cell adhesion-related protein, Pinin37." (PMID 39358554, 2024).
metabolic syndrome (2 papers, 2021 to 2025). A cluster of metabolic risk factors for CARDIOVASCULAR DISEASES and TYPE 2 DIABETES MELLITUS. "In fact, PIWIL1 was detected as a biomarker for a pre-metabolic syndrome state in a mouse model." (PMID 34440082, 2021). "Notably, Piwil1, a gene linked to neurodegeneration, metabolic syndrome and obesity, was up‐regulated in PBMC of MONW but not of MONW‐Lep animals, reflecting early hippocampal changes and leptin's preventive effect." (PMID 40944384, 2025).
Obesity (2 papers, 2025). Accumulation of substantial excess body fat. "Notably, Piwil1, linked to obesity and cognitive decline, mirrors hippocampal changes in PBMC at an early stage." (PMID 40944384, 2025). "However, Piwil1, overexpressed in both tissues, emerged as particularly relevant due to its dual association with obesity and cognitive function." (PMID 40944384, 2025). "Additionally, Piwil1, Spata3, and Trib1 have previously been associated with obesity and its complications." (PMID 40944384, 2025).
sterility (2 papers, 2023 to 2024). "In female golden hamsters, PIWIL1 and PIWIL3 are highly expressed throughout oogenesis and early embryogenesis, while knockout of PIWIL1 leads to sterility, and PIWIL3 deficiency results in subfertility with lagging zygotic development." (PMID 37644029, 2023).
acute lymphoblastic leukemia (1 paper, 2023). Leukemia with an acute onset, characterized by the presence of lymphoblasts in the bone marrow and the peripheral blood. "PIWIL1 polymorphisms’ role in pediatric acute lymphoblastic leukemia (ALL) relapse susceptibility remains undiscovered." (PMID 38023199, 2023).
Ascites (1 paper, 2026). Accumulation of fluid in the peritoneal cavity (between the layers of the peritoneum that lines the abdomen). "The consistent positive association between piR-823 and PIWIL1, especially in older, advanced-stage, and ascites-positive patients, reinforces the hypothesis that PIWIL1 plays a pivotal role in piR-823 biogenesis and function, particularly in more aggressive or advanced diseases." (PMID 41596471, 2026).
asthenozoospermia (1 paper, 2021). "In contrast, the alteration of PIWIL1 in asthenozoospermia patient sperms was irregular, PIWIL1 expression level were increased in the sperms of some asthenozoospermia patients (6 out of 11 patients), but were significantly decreased in 5 patients." (PMID 34326815, 2021). "Therefore, we measured the expression level of MitoPLD and PIWIL1 in the sperms of normozoospermic men and asthenozoospermia patients." (PMID 34326815, 2021).
benign ovarian tumors (1 paper, 2014). "In order to investigate a possible role of this pathway in EOC, we performed semi-quantitative RT-PCR to investigate the expression of PIWIL1, PIWIL2, PIWIL3, PIWIL4 and MAEL in advanced stage serous EOC (n = 25), benign ovarian tumors (n = 19) and normal ovarian tissue (n = 8)." (PMID 24932571, 2014).
cognitive decline (1 paper, 2025). "Additionally, the correlation between Piwil1 expression, working memory performance, and key metabolic parameters, such as increased visceral fat, supports its candidacy as a biomarker for cognitive decline in the MONW phenotype." (PMID 40944384, 2025).
Cognitive impairment (1 paper, 2025). Abnormal cognition is characterized by deficits in thinking, reasoning, or remembering. "Notably, Piwil1 has also been linked to cognitive impairment and neurodegeneration, as it encodes a PIWI‐subfamily protein within the Argonaute family, involved in RNA silencing and neuronal function." (PMID 40944384, 2025).
colon adenocarcinoma (1 paper, 2019). "Analyzing DNA methylation data from 275 colon adenocarcinoma and 19 normal cases from TCGA, a group of CRC tissues (~14%) shows loss of DNA methylation in a CpG island in the promoter region of PIWIL1." (PMID 31694219, 2019).
ductal carcinoma in situ (1 paper, 2020). "PIWIL1 showed slight cytoplasmic immunostaining (HScore: 1) in atypical ductal hyperplasia (10%, n = 1 and ductal carcinoma in situ (10%, n = 1)." (PMID 33008024, 2020).
gastric adenocarcinoma (1 paper, 2014). "It has been reported that BA treatment of human gastric adenocarcinoma AGS cells down-regulates PIWIL1 gene expression." (PMID 25007054, 2014).
metastasis (1 paper, 2021). The spread or migration of cancer cells from one part of the body (where they first appeared) to another. "We suggested that high PIWIL1 expression level was a valuable predictor for poor cancer prognosis in deeper tumor invasion, higher clinical stage, and more lymph node metastasis." (PMID 35003260, 2021).
prostate carcinoma (1 paper, 2019). A carcinoma that arises from epithelial cells of the prostate gland. "The second protein is Piwi-Like RNA Mediated Gene silencing 1 (PIWIL1) which, together with the allelic variant rs10773777, was also detected in prostate cancer cases." (PMID 31354629, 2019).
pulmonary fibrosis (1 paper, 2021). Chronic progressive interstitial lung disorder characterized by the replacement of the lung tissue by connective tissue, leading to progressive dyspnea, respiratory failure, or right heart failure. "In addition, miR-2116-3p was shown to interact with and inhibit PIWIL1, and silencing of PIWIL1 was reported to upregulate FBXW7, which is a component of E3 ubiquitin-protein ligase complex and was observed to induce expression of fibrotic genes including fibronectin during pulmonary fibrosis." (PMID 34715879, 2021).
skin cancer (1 paper, 2016). "PIWIL1,2,3 and PIWIL4 have been found to be mutated in skin cancer." (PMID 27183847, 2016).
testicular tumors (1 paper, 2019). "CpG island methylation is also the mechanism for PIWIL1 down-regulation in testicular tumors." (PMID 31694219, 2019).
cancer (67 papers, 2009 to 2026). A tumor composed of atypical neoplastic, often pleomorphic cells that invade other tissues. "PIWIL1 is frequently associated with cancer stemness, tumor proliferation, and metastasis in various malignancies." (PMID 40558258, 2025). "Dysregulation of PIWIL1 occurs in a broad range of human cancers and is often associated with adverse clinicopathological features and shorter survival of cancer patients." (PMID 33718392, 2021). "Accumulating evidence has revealed that PIWIL1 is implicated in proliferation, apoptosis, invasion, migration, and angiogenesis in a variety of cancers, and it is closely related to poor histological grading of tumor tissue." (PMID 35083142, 2021). "Increasing evidence has shown that overexpression of P-element-induced wimpy-testis (PIWI)-like protein 1 (PIWIL1) was associated with unfavorable prognosis of patients with various types of cancers." (PMID 35003260, 2021). "PIWIL1 is a stem cell renewal gene that has been implicated in promoting cancer cell growth in a number of different types of cancer." (PMID 22591718, 2012). "A study in two large patient cohorts detected PIWIL1 in 15% and 28% of the patients and demonstrated its association with higher Fuhrman grade, more advanced tumor stage, presence of distant metastasis and shorter cancer-specific survival." (PMID 38303021, 2024). "Although the underlying molecular basis of the oncogenic functions of PIWIL1 remains largely unknown, PIWIL1 has been recently reported to mediate the occurrence and progression of human cancers possibly through piRNA-independent mechanisms." (PMID 35003260, 2021). "Therefore, a meta-analysis and systematic review was conducted to synthetically confirm the association between PIWIL1 expression and prognosis in various cancers." (PMID 35003260, 2021). "Although the molecular basis underlying the oncogenic functions of PIWIL1 remains largely unknown, PIWIL1 has been recently found to regulate the occurrence and progression of human cancers possibly through piRNA-independent mechanisms." (PMID 33718392, 2021). "Additionally, cancer specific mutations have been revealed including a PIWIL1 mutant (P1∆17) which lacks an exon 17 and a PIWIL2 mutant (PL2L60) with a truncated PAZ domain." (PMID 33374923, 2020). "Location of PIWIL1 gene polymorphisms that may influence cancer risk." (PMID 38012622, 2023). "Although PIWIL1 has been reported to drive cancer metastasis in piRNA-independent mechanisms, it also functionally cooperates with piRNAs to shape the clinicopathological characteristics of CRC." (PMID 40301858, 2025). "Changes in expression, such as overexpression (e.g., PIWIL1) or downregulation (e.g., PIWIL2), has been identified in several cancers and are associated with poor prognosis." (PMID 40949873, 2025). "It is worth noting that a significant number of studies have shown different ways to regulate cell division and apoptosis of cancer cells by PIWIL1." (PMID 39596284, 2024). "Similar to PIWIL1, several studies have indicated an association between PIWIL2 and cancer cell stemness." (PMID 38303021, 2024). "Genes that have been shown to play a role in this dysregulation include PIWIL1, LIN28A and LIN28B, and have been associated with poorer patient outcomes and more aggressive cancer subtypes." (PMID 36980876, 2023). "As an important member of the PIWI family, PIWI-like protein 1 (PIWIL1) has been reported to be abnormally expressed in many cancers and to mediate various cytological processes, such as cell proliferation, apoptosis, and invasion as well as cell-cycle arrest." (PMID 35464758, 2022). "Taken together, our study unraveled the critical role of PIWIL1 in initiating the interaction of cancer cell metabolism and immune cell response in HCC." (PMID 33633112, 2021). "Given that the expression of PIWIL1 is mostly restricted to the testis and broadly elevated in various tumors, PIWIL1 has the potential to be ideal targets for cancer diagnosis and therapy." (PMID 33718392, 2021).